ARG1 (arginase 1)
Diseases named in the same sentence as ARG1 in open-access papers (continued):
Sharing a sentence is not in itself a finding about the gene and the disease.
tumor (continued). "Glutamine promotes the activation of immature tumor-related myeloid cells and increases Arg-1 expression, which limits the proliferation of T cells through cell cycle arrest." (PMID 36389684, 2022). "In response to IL-4, MDSCs secrete arginase 1 (ARG1) that depletes arginine in the tumor microenvironment." (PMID 35865534, 2022). "Arginase-1-producing cells inhibit T cell-mediated anti-tumor responses by reducing L-arginine levels in the tumor microenvironment." (PMID 36330525, 2022). "Neutrophils augment tumor progression primarily by promoting the production of interleukin-6 (IL-6), arginase-1 (Arginase-1), and vascular endothelial growth factor (VEGF)." (PMID 35295846, 2022). "OATD-02 represents a very promising drug candidate for the combined treatment of tumours, and is the only pharmacological tool that can effectively address the benefits of ARG1/ARG2 inhibition." (PMID 36010962, 2022). "Treatment of CB-1158, an ARG1 inhibitor under clinical trials, has been shown to restore the antitumor immunity exerted by T cells, both in vitro and in vivo syngeneic tumor model, and increase the population of pro-inflammatory macrophages." (PMID 36244976, 2022). "The tumor cells were positive for arginase-1, CD10 (with canalicular enhancement), CD56, cytokeratin 8/18/19, Hep Par-1, β-catenin, LEF1, and androgen receptor (weak positivity)." (PMID 35359182, 2022). "Tumor-cell-derived lactate triggers the expression of vascular endothelial growth factor, Arg1, and the M2-like polarization of TAMs, mediated by HIF-1α, and promotes tumor growth." (PMID 35224683, 2022). "An equal volume (100 μL) of F1–F23 was used to treat BM-PMNs from tumor-free B6 mice followed by qPCR for Arg1 gene expression." (PMID 36377658, 2022). "In mouse tumor models, ARG1 inhibitors, which prevent the breakdown of arginine, increase CD8+ T-cell infiltration and stimulate the production of inflammatory cytokines in the TME." (PMID 35898872, 2022). "The logistic regression model included ARG1, tumor size and number, and platelet counts, and the results showed the model c-index to be higher (0.833), indicating that models incorporating ARG1 expression level had higher prediction accuracy." (PMID 36212404, 2022). "Neutrophil derived Arg1 has been observed to block T cell mediated anti-tumor cytotoxicity through depleting L-arginine in both mouse and human cancers." (PMID 36514901, 2022). "By producing ROS and arginase 1 (ARG1), modulating multiple signaling pathways, and forming neutrophil extracellular traps (NETs), TANs not only promote tumor metastasis and angiogenesis but also suppress NK and T cell cytotoxicity and induce immune tolerance." (PMID 36230914, 2022). "This study showed that the spheroids not only maintained the ARG-1 expression of the original tumor, but also showed differential expression according to the differentiation level of the original tumor." (PMID 35928727, 2022). "In particular, both circulating and tumor-infiltrating MDSCs typically express high levels of Arg-1,32,33 and high arginase activity at the tumor site correlates with decreased cytokine production and low levels of the T-cell receptor (TCR) CD3 ζ-chain." (PMID 35092727, 2022). "We established a nomogram based on the significant predictors identified by binary logistic regression analysis of the univariate and multivariate analysis data, including those on tumor size, tumor number, platelet count, and ARG1 expression." (PMID 36212404, 2022). "Analysis of brain slices showed incorporation of MVs into microglia present in the tumor, which had reduced expression of anti-inflammatory, and thereby anti-tumor genes, such as arg1, CD206 and CD163." (PMID 35813501, 2022). "Compared to IMs, Arg1 expression in AMs is much lower, which is at least one mechanism through which IMs contribute to late-stage tumor growth." (PMID 35778404, 2022).
tumor (continued). "The overall purpose was to activate ARG1-specific T cells to target the tumor microenvironment, strengthen or induce local Th1 inflammation, and potentially eliminate or reprogram ARG1-expressing immune suppressive cells." (PMID 36330525, 2022). "Taken together, these studies suggest that physiologic sources of HGFL support mammary tumorigenesis by promoting tumor cell proliferation, limiting tumor cell death, recruiting M2 (Arginase-1+) macrophages, and suppressing CD4+ and CD8a+ T cell recruitment." (PMID 35626096, 2022). "ARG1 expression is upregulated in TAMs and tumor cells, inhibiting T cell activation by reducing arginine entry into tumor-infiltrating immune cells." (PMID 36532071, 2022). "The tumor-promoting state also regulates immunosuppression by secreting reactive oxygen species and arginase-1, thus limiting T cell-dependent antitumor immunity." (PMID 35912260, 2022). "Previous studies have revealed the fact that ARG1 is involved in anti-inflammation, tumor immunity, and immunosuppression-related diseases." (PMID 35190747, 2022). "MDSCs isolated from the spleen of tumor-bearing mice arrive at the tumor site and became F4/80+ TAMs, characterized by constitutive expression of ARG1 and iNOS." (PMID 36163047, 2022). "The Kupffer cells were isolated by liver perfusion, which confirmed the significantly higher expression of Arg1 in tumor-bearing mice compared to the controls." (PMID 35251971, 2022). "In several xenograft models, ARG1 inhibition has shown delayed tumor growth and enhanced PD-L1 blockade response." (PMID 36091114, 2022). "TEX significantly induced the accumulation of MDSCs expressing cyclo-oxygen-ase 2 (Cox2), IL-6, VEGF, and Arg1 and promoted tumor progression via the PGE2 and TGF-β molecules in TEX." (PMID 35163380, 2022). "Several natural and synthetic compounds have been evaluated in various tumour models, of which CB-1158 (numidargistat), predominantly targeting the extracellular ARG1, is the most advanced in clinical development." (PMID 36010962, 2022). "ARG1 expression in myeloid cells correlated with tumor progression and was accompanied by a systemic drop in ʟ-arginine levels." (PMID 36385153, 2022). "In contrast, tumor-promoting Arg-1+ macrophages were substantially increased in the tumor stages as shown by subclusters Mφ_c3, c8, and c9." (PMID 35316682, 2022). "Tumor cells often escape immune recognition, and the enzyme arginase-1 (ARG1) plays an important role in tumor-mediated immune suppression." (PMID 36330525, 2022). "The results showed that the Arg1 expression in bone marrow G-MDSCs induced by tumor conditioned medium and serum from tumor-bearing mice was significantly upregulated." (PMID 35013108, 2022). "The role of ARG1 in tumor-mediated immune suppression makes it a promising therapeutic target for immune-modulatory vaccines." (PMID 36330525, 2022). "When the immunosuppression of tumor microenvironment was reversed either by PD-L1 depletion or Arg-1-targeted ICI combined therapy, B cells showed an obvious increase." (PMID 35316682, 2022). "The immune modulatory vaccine based on ARG1 can induce anti-tumor immunity and has synergistic anti-tumor effect with Anti-PD-1 checkpoint blockade." (PMID 36505496, 2022). "The loss of miR-155 in MDSCs improved T-cell function and decreased Arg-1, iNOS, Vegf, and Mmp-9 expression, all of which are involved in immune suppression, tumor vascularization, and metastasis." (PMID 36248881, 2022). "We also conducted the Western blot to examine the level of Arg-1 in mice tumor tissues and found that Arg-1 was substantially decreased in the triple therapy compared with radioimmunotherapy." (PMID 35154567, 2022). "The expression of Arg1 in G-MDSCs from different tissues was detected, and the results showed that Arg1 expression was gradually upregulated in bone marrow, peripheral blood and tumor tissue." (PMID 35013108, 2022).
tumor (continued). "In mixed bone marrow chimeric tumor-bearing mice, Arg1-expressing cells also co-expressed IL-6 and the Arg1+ IL-6+ donors were mainly derived from WT donors." (PMID 35778404, 2022). "Arg1 derived from activated neutrophils or dead cells has been shown to induce ER stress in tumor cells, thereby leading to their apoptosis." (PMID 36514901, 2022). "ARG1 is mainly produced by myeloid-derived suppressor cells (MDSCs) as well as more mature myeloid cells that are highly enriched in the tumor microenvironment." (PMID 36385153, 2022). "MDSCs can reduce the ratio of CD8+ T to Treg cells, and the released Prostaglandin E2 (PGE2), arginase 1 (ARG-1), and inducible Nitric oxide synthase (iNOS) can inhibit the cell cycle of T cells and participate in tumor aggregation." (PMID 35037899, 2022). "Furthermore, lactate produced by highly glycolytic tumor cells are considered an immunomodulatory molecule, inducing metabolic polarization of macrophages into M2 TAMs by triggering the expression of M2-associated genes (e.g., arginase 1 (Arg1) and VegfA) in a HIF1α-dependent manner." (PMID 36244976, 2022). "iNOS competes for the same substrate as ARG1 and metabolizes L-arginine to citrulline and NO, which is a key messenger in tumor progression and T-cell activation." (PMID 36163047, 2022). "Cd36−/− BMDMs expressed lower M2 markers (Arg1, Cd206, Il-10) but higher M1 markers (Il-12, Tnfα) compared with WT BMDMs upon incubation with tumor cells or TCM." (PMID 36184646, 2022). "Under the effect of TGF-β present in the TME, neutrophils polarize into pro-tumor N2 neutrophils, which produce proangiogenic factors and exert immunosuppressive activity through the secretion of arginase-1 (Arg1)." (PMID 36072957, 2022). "As a result, increased ARG1 expression dampens T cell-mediated anti-tumor responses in the tumor microenvironment." (PMID 36330525, 2022). "In co-culture of human PBMCs and tumor cells CD36 regulates macrophage response by enhanced lipid uptake and increased expression of pro-tumor genes in modeled TAMs (Arg1, Ccl2)." (PMID 36686729, 2022). "PGE2 is involved in inflammation, angiogenesis, tumor progression via MDSCs recruitment, ARG1 upregulation and regulation of PD-L1 expression on tumor-infiltrating MDSCs, promotion of CXCL12/CXCR4-mediated recruitment of MDSCs." (PMID 35158779, 2022). "IL-9 alters macrophage subsets in the lung and promotes tumor growth in a macrophage- and Arg1-dependent manner." (PMID 35778404, 2022). "Hypoxia tumor-derived exosomal-hsa-circ-0048117 is transmitted to macrophages to promote their polarization to M2 macrophages, which enhance the invasive and migratory ability of tumor cells through secreting IL-10, Arg1, and TGF-β." (PMID 36233088, 2022). "Tumor cell-produced HGFL functions in autocrine to activate RON and downstream MAPK signaling in the tumor cell, which leads to the production of cytokines/chemokines that draw Arginase-1+ macrophages into the TME." (PMID 35626096, 2022). "The mRNA levels of INOS, TNF-α, IRF5, IL-10, TGM2, and Arg-1 in the blood of tumor-bearing mice treated with the exosomes were detected by qRT-PCR." (PMID 35600340, 2022). "On ARG1 vaccine treatment, the patient had SD at the first and second evaluations scan with a tumor growth of 0%-15%." (PMID 36330525, 2022). "Consistently, in our experiments, Ly6Glow neutrophils from infected symptomatic mice have increased Arg1 expression which inhibits T cell proliferation and promotes tumour growth." (PMID 35945238, 2022). "To further illustrate the effect of ART on the immune landscape of in situ tumor microenvironment, we used immunohistochemistry to detect the M1 marker iNOS and M2 marker ARG1 of MDSCs (Gr-1+ cells) and macrophages (F4/80+ cells)." (PMID 35785030, 2022).
tumor (continued). "During the first 7 days after resection, a high expression level of CD86 together with a low expression level of Arg1 were detected at the tumor resection site, indicating an inflammatory activation of the tissue infiltrating myeloid cells." (PMID 35884700, 2022). "ARG1-vaccination activated peptide-specific T cells and induced tumor growth control upon vaccination." (PMID 36330525, 2022). "Mechanistically, ILC2-derived IL-4 and IL-13 in response to IL-25 signaling activated tumour M-MDSCs derived from Apc1322T/+ mice to express Arginase 1 (Arg1) and suppress CD8+ T cells." (PMID 36263033, 2022). "In a tumor setting, an ARG1-induced depletion of L-arginine impairs T cell receptor (TCR) signaling through the downregulation of TCR ζ chain expression, induces T cell cycle arrest, limits T cell differentiation, and reduces cytokine production." (PMID 36330525, 2022). "To support this, we recently showed the anti-tumor effects of ARG1-based vaccination in several different murine cancer models." (PMID 36330525, 2022). "A switch in myeloid cell activation was observed by day 14, when a significant increase of Arg1 expression was identified in the tumor resection area and was further sustained up to the 21st day." (PMID 35884700, 2022). "The fact that Arg1-expressing macrophages can rescue tumor growth in Il9r−/− mice indicates Arg1 is a critical effector in IL-9-macrophage mediated tumor growth." (PMID 35778404, 2022). "Arg1+ macrophages from tumor bearing mice secreted more IL-6 than Arg1- macrophages, and were capable of inducing tumor cell migration in the presence of IL-9." (PMID 35778404, 2022). "COX-2 is also implicated in increasing MDSC proliferation, which is correlated with an upregulation of arginase-1 and iNOS expression in murine tumor-infiltrating leukocytes, thereby stimulating cancer cell proliferation." (PMID 35406621, 2022). "Arginase 1 and 2 are drivers of multiple immunosuppressive mechanisms and tumour-specific metabolic adaptations." (PMID 36010962, 2022). "Entinostat reprogrammed tumor-infiltrating MDSCs by significantly inhibiting the expression of ARG1, iNOS and COX2 and suppressing the function of immunosuppressive MDSCs, thereby overcoming immune resistance." (PMID 36163047, 2022). "At the tumor site, MDSCs affect T cells to form an immunosuppressive microenvironment by producing Arg-1, iNOS, IDO, NOX2, and immunosuppressive cytokines." (PMID 34841231, 2021). "Garcinia livingstonei T. Anderson (GLT) elevates the expression level of iNOS and IL-12, and reduces the expression levels of IL-6, TNF-α, Arg-1, and IL-1β on TAMs to impede the tumor progression through the inhibition of STAT3, JNK, and ERK signaling pathway." (PMID 33748122, 2021). "Total flavonoid from Glycyrrhiza inflata Batalin (GIB) and its important ingredient, isoliquiritigenin (ISL), reverse the polarization of M2 phenotype macrophages to retard tumor invasion through inhibiting the gene and protein expression of Arg-1." (PMID 33748122, 2021). "Cancer cells cause anergy of NK cells by secreting a number of immunosuppressive factors, including IL-10, TGF-β, PGE2, ADO, and two tumor enzymes: arginase 1 (Arg1) and indolamine 2,3-dioxygenase (IDO)." (PMID 34209508, 2021). "A mouse tumor model showed that PDE5 inhibition with tadalafil attenuates MDSC suppressive capabilities by downregulating ARG1 and iNOS expressions, thus increasing T cell infiltration and activation." (PMID 34336860, 2021). "In a tumor context, MDSCs and M2 macrophages deplete arginine from the environment via the enzyme arginase 1 (Arg1)." (PMID 34885023, 2021). "It is of note that the experimental set-up of this study resulted in some diffuse weak to moderate staining of stroma as well as of tumor tissue adjacent to strongly arginase-1 positive normal liver cells." (PMID 34943588, 2021).
tumor (continued). "On the other hand, arginine metabolism to ornithine, a precursor of polyamines, by ARG1 is necessary for macrophage homeostatic functions and is usurped in TAMs to support tumor growth." (PMID 34831183, 2021). "Expression of Arginase 1 on TAMs accelerates the metabolism of L-arginine to urea and L-ornithine, thereby further dampening T-cell recognition of tumor antigens and the antitumor immune response." (PMID 34178692, 2021). "MDSCs exert immune-suppressive effects to promote tumor growth and inhibit T cell activation through impairing immunity by elevating arginase-1, nitric oxide (NO), and ROS." (PMID 33413697, 2021). "Recently, two distinct immune cell populations expressing ARG1 have been discovered within the TME of a fibrosarcoma tumour mouse model." (PMID 34685679, 2021). "Tumour exosomal PGE2 and TGF-β strengthen the induction of MDSCs, activate the upregulation of Cox2, IL-6, VEGF, and ARG-1 in MDSCs, and promote T-exosome-mediated tumour proliferation." (PMID 34193120, 2021). "Although identifying and targeting immuno-suppressive TAM subpopulations based on single markers, such as CD163 or Arg-1, has shown positive results, developing these approaches remains challenging due to their variation between species and tumor types." (PMID 34572807, 2021). "A successful analysis of 12,047 cancers from 117 different tumor entities revealed a pattern of expression for arginase-1 that strongly correlated with the findings in normal tissues." (PMID 34943588, 2021). "Two enzymes participating to arginine-metabolism NOS2 and ARG1 are up-regulated in tumor specimens where act as key mediators for T cell suppressive mechanisms." (PMID 34675917, 2021). "Monocytes are recruited to the TME and differentiate into tumor-associated macrophages (TAMs), a particular cell type that expresses TGF-β, iNOS and Arg-1 and resembles the M2 phenotype." (PMID 34571894, 2021). "Results of RT-qPCR showed a significant downregulation in the expression of Arg-1 and iNOS mRNA in the tumor tissues of the three intervention groups, compared with the NS group." (PMID 34055197, 2021). "For example, Arg-1 is mainly secreted by tumor-infiltrating myeloid cells, including TANs, and can directly suppress T lymphocytes and participate in tumor immune escape." (PMID 33814009, 2021). "Early studies have shown that TAMs expressing high levels of ARG1 are key effectors of tumor immune evasion, and that the inhibition of ARG1 reduces the tumor growth, as demonstrated in the LLC transplantable mouse model." (PMID 34831183, 2021). "This activity of ARG1 promotes tumor growth, metastasis and neovascularization, and it is associated with poor prognosis in different cancer types." (PMID 34885023, 2021). "PD-L1 and cytotoxic T-lymphocyte-associated protein 4 (CTLA-4), arginase 1 (ARG1), high-mobility group box 1 protein (HMGB1), and TGF-β are among the proteins found in tumor cell exosomes related to immunosuppression." (PMID 34685513, 2021). "MDSCs also suppress T cell anti-tumor actions via programmed death-ligand 1 (PD-L1), arginase (Arg-1), interleukin-10 (IL-10) and transforming growth factor beta (TGF-β)." (PMID 34531850, 2021). "We observed that the majority of HPV+ patients have a lower tumor stage (p < 0.0001 by Fisher test) and lower ARG1 mRNA level compared to HPV− patients (p = 0.0009)." (PMID 33807310, 2021). "Blocking of CXCL10/CXCR3 signaling in vivo shifts macrophage populations to a tumor-promoting (Ym1+, Fizz+, Arg1+) phenotype, increases fibrosis, and mediates progression of lesions, highlighting the importance of this pathway in PDA development." (PMID 34328416, 2021). "As expected, we found that tumor cell conditioned media induced high Arg-1 expression on BM-myeloid cells from NTB mice, a response that was not sensitive to VEGF blockade." (PMID 34673569, 2021).